INS (insulin)
Diseases named in the same sentence as INS in open-access papers (continued):
Sharing a sentence is not in itself a finding about the gene and the disease.
diabetes (continued). "Previous studies regarding the therapeutic effectiveness of Lactobacillus species on diabetes and its complications were focus on increasing insulin sensitivity or delaying the onset of glucose intolerance, hyperglycemia, hyperinsulinemia, dyslipidemia, and oxidative stress." (PMID 23590862, 2013). "Inflammation affects insulin signalling and increases beta-cell death, and markers of inflammation, such as elevated interleukin 6 (IL-6) and C-reactive protein (CRP) levels, have been found to be associated with future diabetes risk." (PMID 23843750, 2013). "ROS induced damage to the insulin producing pancreatic beta-cells induces diabetes." (PMID 24719624, 2013). "Even after the discovery and use of insulin and availability of existing modern antidiabetic agents such as sulphonylureas, biguanides, and incretins, the search of more effective drugs of plant origin for the treatment of diabetes continues as an alternative." (PMID 24319481, 2013). "In contrast, more women were taking insulin and OHAs at admission and discharge, but this may well reflects their higher prevalence of diabetes." (PMID 23405162, 2013). "Whether this association reflects a contribution of endothelial dysfunction to accelerated decline in insulin sensitivity, or represents only an epiphenomenon accompanying pre-diabetes, remains to be elucidated." (PMID 23578341, 2013). "Deregulation of processes downstream of insulin may result in diseases such as diabetes, hypertension and cancer." (PMID 24400038, 2013). "If this were to hold in vivo it could explain hyperinsulinaemia as a result of gap junction loss as well, when steady state levels of circulating plasma insulin in diabetics continue to be high even in fasting conditions." (PMID 23936417, 2013). "Automobile accidents have been associated with lower HbA1c in a largely insulin-treated population, and in people with type 1, but not type 2, diabetes." (PMID 23121373, 2013). "It is shown that diabetes and injection of insulin may be attributed to more incidences of cardiovascular events." (PMID 23983773, 2013). "Furthermore, HDL exerts insulin-sensitizing effects enhancing the glucose disposal in type 2 diabetes mellitus patients." (PMID 24267726, 2013). "Impairment of insulin secretion in diabetes increases the release of free fatty acids (FFA) into the liver, and it may cause an increase in triglyceride production." (PMID 23737649, 2013). "Some reports suggest that adiponectin plays an important role in insulin actions and hypoadiponectinemia may result in insulin resistance and diabetes mellitus." (PMID 23573411, 2013). "25.4% of the patients had an unacceptable HbA1c level of >8.0% and the odds of this were higher (p < 0.05) in patients with the following characteristics: younger age, longer diabetes duration, presence of insulin treatment, and poorer compliance to medication." (PMID 23725198, 2013). "Thus, FYGL was an effective antidiabetic agent by enhancing insulin secretion and decreasing hepatic glucose output along with increase of adipose and skeletal muscle glucose disposal in the late stage of diabetes." (PMID 23874589, 2013). "Similarly as described by the participants for their initial insulin resistance, their concerns and beliefs about diabetes and insulin had played important factors in their treatment decision-making." (PMID 24164794, 2013). "Self-report of diagnosis augmented with free text data indicating diabetes as a chronic condition and/or use of insulin among medications used was able to identify participants with diabetes with high sensitivity and specificity compared to available administrative data collections." (PMID 24245780, 2013). "Type 2 disease, the most common form treated in primary care, is progressive and aggressive insulin intensification to safely control diabetes may be required over time." (PMID 27536441, 2013).
diabetes (continued). "In conduction with the previous studies, the current study aims to investigate the effect of preexisting experimentally induced diabetes mellitus in rat dams on the glycemic status, insulin resistance, and β-cell function and integrity in their offspring at different postnatal periods." (PMID 23998129, 2013). "Insulin is a key regulator of blood glucose and insufficient insulin leads to diabetes." (PMID 23630453, 2013). "Nevertheless, insulin depletion occurring with increasing duration of diabetes may limit insulin action and hence protect against PCa." (PMID 24058525, 2013). "Diabetes is dreadful lifestyle disorder of 21st century caused due to lack of insulin production or insulin physiological unresponsiveness." (PMID 23822656, 2013). "In Puerto Rico, where the Vieques military base is located, very high rates of diabetes were also observed (25% of the population has diabetes), Moret states that uranium interacts with the biochemical mechanism of insulin at a cellular level and damages the pancreas." (PMID 23603867, 2013). "Therefore, 'trial of insulin’ can be promoted to diabetes patients to provide them the opportunity to gain such positive experience." (PMID 24164794, 2013). "β 1-AR selective antagonists, as well as carvedilol, the latter shown to improve insulin-sensitivity, could possibly represent a valid alternative for HF patients with concomitant diabetes." (PMID 24294204, 2013). "In addition it has been shown that DC grown in autologous serum were able to prevent diabetes but only when pulsed with insulin-derived peptides." (PMID 24367363, 2013). "Future studies in the C/EBPα independent pathways leading to insulin responsiveness may reveal new targets to diabetes treatment." (PMID 23326314, 2013). "Nocturnal hypoglycemia may be the most common type of hypoglycemia in individuals with diabetes using insulin and is particularly worrisome because it often goes undetected and may lead to unconsciousness and even death in severe cases." (PMID 23737776, 2013). "Insulin-dependent PI3K/Akt signaling can also improve diabetes by activating insulin receptor." (PMID 23690860, 2013). "However, diabetes duration was shorter among patients using OADs only (4.76 years) and longer among patients using OADs and insulin (7.12 years; p < 0.0001)." (PMID 23800082, 2013). "Diabetes is a metabolic disorder of multiple etiologies characterized by chronic hyperglycemia with disturbance of carbohydrate, fat, and protein metabolism resulting from defects in insulin secretion, insulin action, or both." (PMID 23509685, 2013). "It is validated against serum measures of the insulin in people with diabetes." (PMID 24353253, 2013). "Insulin administration in patients with type 2 diabetes mellitus (T2DM) has proved to be the most effective treatment modality, which should be initiated early in the course of the disease in case lifestyle modification and/or metformin administration fail to achieve recommended glycaemic standards." (PMID 23916120, 2013). "Theoretically, diabetes treatments involving insulin or metformin may increase or decrease hyperinsulinemia, and these changes may influence the incidence or treatment results in different cancers." (PMID 23383099, 2013). "Natural APSL could promote the repair of damaged islets and the secretion of insulin to treat diabetes." (PMID 23652883, 2013). "Diabetes remission was less likely in patients with lower BMI than those with higher BMI, in patients with longer than shorter duration and in patients with lesser than greater insulin reserve." (PMID 23515973, 2013). "Lastly, while insulin use did not further risk stratify for low drug concentrations among diabetics, little else was known about diabetic disease severity." (PMID 24349775, 2013). "Thus, we performed this meta-analysis to determine whether insulin use was associated with PCa risk in patients with diabetes mellitus (DM)." (PMID 24282613, 2013).
diabetes (continued). "In mice, loss of Cx36 does not cause overt diabetes, but causes intolerance to post-prandial glucose levels as a result of the in vivo decrease in the oscillations of circulating insulin." (PMID 24278783, 2013). "In addition, recent evidence suggests that LM25 provides similar glycemic control to that of insulin lispro plus glargine in insulin-naïve patients with uncontrolled diabetes on AHAs." (PMID 24011173, 2013). "Also, high concentrations of triglyceride, cholesterol, LDL, and VLDL were detected, probably due to inadequate insulin treatment, poor control of diabetes, and unhealthy nutritional intake." (PMID 23748069, 2013). "You have to plan your exercise as well” (6 years of insulin use/ 10 years of having diabetes)." (PMID 24164794, 2013). "Relatively or absolutely inadequate secretion of insulin leads to the development of diabetes." (PMID 23424659, 2013). "Hence the main defense of patients with insulin-treated diabetes is subjective recognition of symptoms such as sweating, hunger, and tremor." (PMID 23543638, 2013). "The aim of this retrospective study was to examine whether patients with diabetes mellitus (DM) using insulin glargine have a higher tumor stage of breast carcinoma in comparison to patients using other types of insulin." (PMID 24131755, 2013). "However, few studies have focused on diabetes treatment with insulin, one of the most reliable agents for glycemic control." (PMID 24011395, 2013). "As there is various knowledge-seeking methods found to be practiced by the participants in this study, easy access to information related to diabetes and its treatment should be provided through multiple strategies (e.g. one-stop centre, website or pamphlets) to enhance insulin acceptance." (PMID 24164794, 2013). "Improved diabetes control using insulin intensification typically results in weight gain." (PMID 27536441, 2013). "The reason for an increase in insulin requirement may be due to insulin resistance with increasing age and diabetes duration." (PMID 23967077, 2013). "Insulin-naïve subjects with type 2 diabetes [n = 458, age: 56 years, diabetes duration: 7.7 years, glycosylated haemoglobin (HbA1c):8.9% (74 mmol/mol)] were randomized (1:1) to once-daily IDeg or Sita (100 mg orally) as add-on to stable treatment with 1 or 2 oral antidiabetic drugs (OADs)." (PMID 23577643, 2013). "As the relationship becomes longer, the number of prescribed drugs, insulin use, and diabetes complications could affect the goal of diabetes education, and the communications could be tailored to these conditions." (PMID 23522359, 2013). "However, in a subset of women with severe hyperglycemia, poorly controlled diabetes, vascular complications or excessive insulin administration, intrauterine growth restriction is a frequent observation." (PMID 23516451, 2013). "Nowadays the agents used for diabetes treatment mainly are synthetic drugs and insulin." (PMID 23874589, 2013). "In comparison, an analysis was conducted using data from the National Health and Nutrition Examination Survey (NHANES) to assess diabetes prevalence and therapeutic target achievement for US patients using diet and exercise, oral antihyperglycaemic medications and/or insulin." (PMID 23078638, 2013). "It has now been recognized that a compensatory period (i.e., a compensatory increase in insulin secretion secondary to insulin resistance with little change in the glucose levels) exists before the diagnosis of diabetes, and the insulin secretion decreases after the diagnosis of diabetes." (PMID 23483954, 2013). "In conclusion, C-peptide measurement is an inexpensive, widely available test that may assist the clinical management of diabetes, particularly in insulin-treated patients where there is uncertainty about diabetes subtype." (PMID 23413806, 2013). "In concert, insulin resistance and reduced insulin secretion lead to overt diabetes." (PMID 23460912, 2013).
diabetes (continued). "“I was scared of insulin injection” (2 years of insulin use/ 5 years of having diabetes)." (PMID 24164794, 2013). "Structural studies elucidate how each of the three ligands, insulin, IGF-1, and IGF-2, interacts differently with isoforms A and B of the insulin receptor and with type I IGF receptor and explain how these protagonists contribute to diabetes-associated cancer." (PMID 23983688, 2013). "In conclusion, the preexisting diabetes mellitus and hyperglycemia before and during gestation may increase risks of glucose intolerance, insulin resistance, and impaired insulin sensitivity and β-cell function in offspring." (PMID 23998129, 2013). "Possible barriers to adherence to the recommended standards and optimal diabetes care in our study include a fragmented delivery system, the lack of a system that facilitate the appropriate use of scheduled insulin therapy and low institution support for inpatient multidisciplinary team training." (PMID 24499564, 2013). "According to 2006 American Diabetes Association’s recommendation, SMBG is regarded as an essential aspect of diabetes management in insulin-treated patients and a desirable aspect in non-insulin treated patients with diabetes." (PMID 23876067, 2013). "Moreover, changes in insulin secretion after several days of glucose infusions in rats resemble those seen in diabetics, yet such infusions suppress free fatty acid (FFA) levels." (PMID 23363033, 2013). "First introduced into clinical practice in 1969, glibenclamide (US adopted name, glyburide) is known best for its use in the treatment of diabetes mellitus type 2, where it is used to promote the release of insulin by blocking pancreatic KATP [sulfonylurea receptor 1 (Sur1)-Kir6.2] channels." (PMID 24275850, 2013). "Insulin is known to regulate multiple cellular functions and is used for the treatment of diabetes." (PMID 23762265, 2013). "The exacerbation of diabetes concerned a 45 year old Caucasian male with HCV infection since 2000 and ongoing diabetes treated with metformin, who experienced significant worsening of blood glucose control on study day 22 requiring the introduction of insulin which persisted until study conclusion." (PMID 23717490, 2013). "Since food intake influences the amount of insulin required to meet blood glucose target goals, the food especially carbohydrate intake could contribute to the pathology of diabetes." (PMID 26317014, 2013). "Hyperglycemia and abnormal insulin metabolism altogether with vascular lesions might contribute to the cerebral neuropathology related to type 2 diabetes mellitus." (PMID 23593231, 2013). "Additionally, serum glucose enhances the compensatory production of insulin, a strong growth factor, in the early stage of diabetes and in insulin resistant states." (PMID 23372798, 2013). "To date, the majority of studies evaluating stem cell transplantation in diabetes have focused on the ability of the administered cells to regenerate and/or protect the insulin-producing beta cells of the pancreas as a means of providing improved glucose control and reducing diabetic complications." (PMID 24007410, 2013). "Consequently, patients misdiagnosed as type 1 diabetes and treated with insulin can be switched to oral SU therapy once the genetic diagnosis of HNF1A diabetes is made." (PMID 23766565, 2013). "Her diabetes was well-controlled prior to pregnancy on a basal bolus regimen, but she was converted to insulin pump therapy in the first trimester – by the third trimester, she was using 35–40 units of soluble insulin daily." (PMID 24616775, 2013). "In the present study, regardless of the model used, longer duration of diabetes and previous treatment with insulin, were found to be associated with a lower rate of remission, a finding which is consistent with most published analyses." (PMID 23537494, 2013).
diabetes (continued). "Insulin glycemic control in diabetes may restore the neuroprotective effects of anesthetic post-conditioning by modulation of brain mitoKATP channel." (PMID 23991188, 2013). "For instance, molecules such as carvedilol, which have been demonstrated to ameliorate insulin sensitivity, could be useful in patients with concomitant diabetes." (PMID 24294204, 2013). "In addition, recent evidence suggests that LM25 provides a similar clinical effect on glycemic control compared with insulin lispro plus glargine in insulin-naïve patients with uncontrolled diabetes on AHAs." (PMID 24011173, 2013). "Similarly, zinc acts as an antioxidant in order to reduce oxidative stress, it is essential for the function of SOD and is also involved in insulin synthesis which are altered in diabetes." (PMID 24982856, 2013). "Insulin therapy improves β-cell function in early stages of diabetes by mechanisms that may exceed alleviation of glucotoxicity." (PMID 23408938, 2013). "We hypothesize that the metformin group will have a greater reduction in insulin resistance compared to the switch antipsychotic group because metformin is a diabetes medication that is specifically used to improve insulin sensitivity." (PMID 23947389, 2013). "Although the estimate for change in total adiponectin decreased by 34% when change in weight was added to the model, these results indicate that improvements in total adiponectin level contributed to improved insulin sensitivity above the usual clinical markers of diabetes." (PMID 29755881, 2013). "This suggests that insulin use is a burden on quality of life in diabetes." (PMID 24349036, 2013). "In addition to their positive modulatory roles, certain small G proteins also contribute to the metabolic dysfunction and the demise of islet beta-cells that has been observed in in vitro and in vivo models of impaired insulin secretion and diabetes." (PMID 23841104, 2013). "Diabetes mellitus is a metabolic disorder of multiple aetiology that is characterized by chronic hyperglycaemia affecting carbohydrate, fat and protein metabolism, which results from improper insulin production." (PMID 24039701, 2013). "As a result of this higher contact frequency, physicians may have more opportunities to introduce insulin to the hyperglycemia treatment of depressed people with diabetes." (PMID 24223860, 2013). "This is important since newcomer granules accounting for a much bigger portion of β-cell total insulin exocytotic capacity and could be targeted for more effective therapy to treat diabetes than the predocked granules." (PMID 23844030, 2013). "Diabetes induces several changes in different hormonal systems including insulin, insulin-like growth factors, estrogen, and other growth factors, all of which may affect the risk for breast cancer development." (PMID 23401790, 2013). "The American Diabetes Association (ADA) provides evidence-based nutrition recommendations that aim to reduce the risk of diabetes and cardiovascular disease (CVD), with goals that include regulating blood glucose and insulin levels, and improving lipid and lipoprotein profiles." (PMID 24152749, 2013). "For example, Burkholderia pseudomallei has a specific and high affinity binding site for insulin, which might explain why in human patients with diabetes the progression of melioidosis has been shown to be influenced by serum insulin levels." (PMID 24381789, 2013). "The expected associations with better diabetes-specific quality of life were evident, such as increased income, not on insulin, better glycaemic control and older age." (PMID 24131673, 2013). "Diabetes is characterized by metabolic dysregulation primarily of carbohydrate metabolism, manifested by hyper-glycemia resulting from defects in insulin secretion, impaired insulin action, or both." (PMID 23841105, 2013).